PRL (prolactin)
Diseases named in the same sentence as PRL in open-access papers (continued):
Sharing a sentence is not in itself a finding about the gene and the disease.
psychosis (continued). "However, the findings of a recent study in patients with first episode psychosis indicated that such reproductive adverse events can occur even when prolactin levels are normal." (PMID 23206324, 2012). "The main medications used to maintain normal prolactin levels are dopamine agonists, such as cabergoline and bromocriptine, which may not be the ideal choice for patients with a history of psychosis as they can increase the risk of psychiatric decompensation." (PMID 38143631, 2023). "From our cross-sectional design we do not know whether prolactin could be a biomarker related to the risk of transition to psychosis." (PMID 24586772, 2014). "Second, when exposed to further stressors, increases in prolactin levels may indirectly—as in Riecher-Rossler's proposal of a feedback increase in dopamine, which may also be exaggerated—lead to some of the symptoms of psychosis." (PMID 24800074, 2014). "A meta-analysis of PRL blood concentrations revealed elevated levels in antipsychotic-naïve patients experiencing a first episode of psychosis (AN-FEP), indicating that PRL is a potential biomarker for this illness." (PMID 39812050, 2025). "Nevertheless, the assessment of prolactin response to antipsychotics must be conducted taking into account several other factors that might have an influence on prolactin serum levels, such as participants’ gender, age, psychopathology, type of medication, duration of psychosis." (PMID 32017792, 2020). "To verify this hypothesis we compared PRL levels, glycometabolism parameters and lipid profile between a sample of drug-naive adolescents in the acute phase of FEP and a control group of subjects at clinical high risk (CHR) of developing psychosis, age and sex matched." (PMID 30068291, 2018). "The main findings of this study were significantly higher values of PRL and HOMA-IR in the sample of early onset drug-naive FEP when compared with subjects at CHR of developing psychosis." (PMID 30068291, 2018). "A meta-analysis has uncovered that drug-naïve patients experiencing a first episode of psychosis (FEP) exhibit elevated blood concentrations of adrenocorticotropic hormone (ACTH) and prolactin (PRL), along with lower levels of thyroid-stimulating hormone (TSH)." (PMID 38671962, 2024). "Key symptoms of the presented clinical picture are: childhood-onset complex and treatment-resistant psychosis/catatonia, pronounced behavioral problems, fatigue, absent thirst perception, hypernatremia and elevated prolactin levels." (PMID 37539324, 2023). "Finally, one study (reviewed by Riecher and Studerus) reported increased prolactin levels in patients with later transition, although it is unclear whether these represent a stress-related epiphenomenon, or contribute to the emergence of psychosis via pro-inflammatory or cognitive-mediated pathways." (PMID 37640731, 2023). "The levels of serum prolactin were found to be elevated, not dissimilar, or even reduced in women compared to men in the included studies; hence the need for greater personalization when taking care of patients with psychosis." (PMID 34945748, 2021). "The production of prolactin (PRL) is inhibited by dopamine release in the hypothalamo-pituitary circuit and can be increased by blocking type 2 (D2) dopamine receptors; therefore HPRL in patients with psychosis seems to be related mainly to the D2-receptors affinity of antipsychotic drugs." (PMID 30068291, 2018).
osteoporosis (43 papers, 2010 to 2025). A condition of reduced bone mass, with decreased cortical thickness and a decrease in the number and size of the trabeculae of cancellous bone (but normal chemical composition), resulting in increased fracture incidence. "In the long term, lowering prolactin levels has been shown to reduce the risk of osteoporosis, and by implication, the risk of falls." (PMID 39120186, 2024). "The study also commented that the increase in PRL level is an important risk factor leading to osteoporosis after long-term use of typical antipsychotics." (PMID 34526046, 2021). "Our binary regression logistic analysis showed that PRL and E2 levels were independently associated with osteoporosis." (PMID 33987015, 2021). "Rather, the results suggested that gonadal hormones, namely, PRL and E2, are important to osteoporosis risk." (PMID 33987015, 2021). "Given the multicausal nature of osteoporosis‐related fractures, it is challenging to disentangle the specific risk contribution of a prolactin‐elevating antipsychotic such as risperidone." (PMID 31545521, 2020). "Antipsychotic agents can increase circulating serum prolactin levels, potentially leading to osteoporosis and increased risk of bone fracture." (PMID 31487309, 2019). "This association is of particular concern given the known link between antipsychotics and osteoporosis risk via raised prolactin levels." (PMID 29388522, 2018). "Antipsychotic medication was identified as a risk factor for osteoporosis in the narrative review, with PRL-raising antipsychotics having a larger impact on bone health than PRL-sparing medication." (PMID 27696144, 2016). "The blocking effect on dopamine D2 receptor can elevate prolactin secretion, which may be linked to elevated risk of osteoporosis." (PMID 39268461, 2024). "Overall, our previous description pointed out that long-term use of RPD might promote the risk of osteoporosis due to elevated prolactin levels." (PMID 39268461, 2024). "In such patients, it is also important to check for secondary causes of osteoporosis including myeloma and coeliac screen, plasma parathyroid level, testosterone, prolactin, tests of cortisol excess and thyroid function tests as appropriate in line with international guidelines." (PMID 37428295, 2023). "Moreover, high PRL negatively affects gonadal function in both sexes, acting as an additional risk factor for osteoporosis." (PMID 36904090, 2023). "Previous studies have reported that prolactin (PRL) is related to osteoporosis risk." (PMID 35757392, 2022). "Moreover, logistic regression analysis confirmed that PRL and E2 were independent predictive factors associated with osteoporosis after controlling for other known associated factors." (PMID 33987015, 2021). "Increased prolactin and reduced estradiol levels are significantly associated with osteoporosis." (PMID 33987015, 2021). "Increased levels of relaxin, excessive weight gain, hyperlordosis, weakness of the pelvic ligaments, osteopenia caused by increased level of prolactin, and osteoporosis of pregnancy may contribute to the development of sacral fractures." (PMID 26246926, 2015). "Very recently, Graham and others published a literature review showing that first generation antipsychotics and certain second generation agents such as risperidone show high prolactin elevations and are associated with an increased risk of osteoporosis and fracture." (PMID 23968123, 2013). "By lowering estrogen levels, high prolactin induces osteoporosis and lowers the efficacy of certain antipsychotics." (PMID 39120186, 2024). "In conclusion, the decline in the gonadotropin-releasing hormone (GnRH) resulting from heightened levels of prolactin can contribute to a reduction in bone mineral density, a key aspect of osteoporosis." (PMID 38338751, 2024).
osteoporosis (continued). "Risperidone is one of the widely prescribed antipsychotics; however, long-term use is usually accompanied by various side effects, such as weight gain, extrapyramidal symptoms, prolactin elevation, and osteoporosis." (PMID 39268461, 2024). "For osteoporosis, many studies have suggested that long-term treatment with RPD increases the risk of osteoporosis by elevating serum prolactin levels." (PMID 39268461, 2024). "Our results indicated that male chronic schizophrenia patients with high PRL levels were more likely to have reduced BMD, increased bone loss and even osteoporosis." (PMID 32788631, 2020). "It is associated with a greater and more frequent elevation of circulating prolactin level compared with other atypical antipsychotics 4, 5, and because of this fact, there has been a concern that risperidone may be associated with an increased risk of osteoporosis‐related fractures." (PMID 31545521, 2020). "Raised prolactin can be asymptomatic, leading to various acute adverse effects, and can also result in long-term medical problems, including osteoporosis." (PMID 28289436, 2017). "There was a significantly increased rate of osteopenia, osteoporosis, and ultimately vertebral fractures in a study comparing women with prolactinomas to those with normal prolactin levels." (PMID 27446618, 2016). "In that study, osteoporotic conditions (low bone mineral density) were greater in prolactin‐inducing SGAs (57.1% osteoporosis, 19.0% osteopenia) and prolactin‐sparing SGAs (19.1% osteoporosis, 47.6% osteopenia) compared to no treatment (18.2% osteoporosis, 4.5% osteopenia)." (PMID 40329580, 2025). "However, there are a variety of side effects associated with RPD treatment, including weight gain, extrapyramidal symptoms, prolactin elevation, and osteoporosis." (PMID 39268461, 2024). "Although PRL is essential for bone growth and homeostasis, patients with pathological high PRL concentrations show increased bone resorption and suppressed bone formation activity, which eventually leads to osteoporosis." (PMID 32668736, 2020). "The limitations of our work include a lack of information on other factors that may also contribute to osteoporosis, such as nutrition, calcium/vitamin D intake, and levels of parathyroid hormone and prolactin." (PMID 31019532, 2019). "When administered to such a young patient group, PRL-raising medications may prevent an optimum peak bone mass from being achieved, thus reducing lifelong BMD and predisposing patients to osteoporosis." (PMID 27696144, 2016). "Therefore we hypothesized that RPD may cause abnormal bone mineralization by elevating the level of prolactin, eventually leading to osteoporosis." (PMID 39268461, 2024). "Despite the immune-modulator action, PRL impacts bone metabolism, contributing to low BMD and osteoporosis." (PMID 36904090, 2023). "PRL levels were slightly higher in men with osteoporosis than in the men without osteoporosis (15.60 ± 5.93 vs. 14.26 ± 5.99 ng/ml, p = 0.109)." (PMID 36313749, 2022). "Patients with osteoporosis tended to be older, have a longer disease course, have a higher BMI, have significantly higher PRL levels, and have lower E2 levels than patients without osteoporosis." (PMID 33987015, 2021). "Regarding gonadal hormones, we found significantly higher prolactin, but lower estradiol, levels in patients with osteoporosis than in those without osteoporosis (both P < 0.05)." (PMID 33987015, 2021). "Specifically, we found that patients with osteoporosis had significantly higher PRL levels but lower E2 levels than patients without osteoporosis, which is similar to the findings of previous studies." (PMID 33987015, 2021). "Recently, an increasing number of studies have suggested that V. segetalis extract has various bioactivities, such as prolactin- (PRL-) like, estrogen-like, antitumor, antiangiogenesis, and antioxidant activity, and it is also shown to dilate blood vessels and relieve osteoporosis." (PMID 33996757, 2021).
systemic lupus erythematosus (43 papers, 2007 to 2025). An autoimmune multi-organ disease typically associated with vasculopathy and autoantibody production. "•Lower E2 levels in pregnant lupus patients vs. pregnant controls.•Prolactin levels positively associated with severity.•Flares more common with increase in estrogen." (PMID 31110493, 2019). "A significant association between PRL and disease flairs was found in systemic lupus erythematosus and rheumatoid arthritis." (PMID 29483903, 2018). "Systemic lupus erythematosus (SLE) has shown an association with high levels of prolactin, low levels of dehydroepiandrosterone (DHEA), and induction of inflammatory cytokines in the serum of patients with the disease." (PMID 26583155, 2015). "Recently, a study confirmed that prolactin levels are associated with lupus activity, lupus anticoagulant, and poor outcome in pregnancy." (PMID 25973434, 2015). "High serum levels of sex hormones, especially prolactin and estradiol, have been considered to be associated with the lupus disease activity." (PMID 25973434, 2015). "Additionally, in Sle3/5 R4A-γ2b C57BL/6 mice that express both the H chain transgene and the Sle3/5 lupus susceptibility range, PRL decreases the T1:T2 B ratio and promotes autoreactive B-cell accumulation in splenic follicles." (PMID 38680484, 2024). "Indeed, a significant association between PRL levels and disease activity was found in systemic lupus erythematosus, rheumatoid arthritis, and peripartum cardiomyopathy patients, therefore breastfeeding should not be encouraged among those patients." (PMID 29483903, 2018). "The TT genotype was associated with higher expression of prolactin in lupus patients which may be due to the majority demographic in this study being African American women." (PMID 26583155, 2015). "Systemic lupus erythematosus (SLE) mainly affects females at reproductive age, which has been associated with hormones, such as prolactin (PRL)." (PMID 36389691, 2022). "Perhaps the key to unravelling the role of PRL in lupus is determining the source, given that lymphocytes, skin and hair follicles are all extra-pituitary sources." (PMID 39000207, 2024). "Whilst it now seems clear that PRL is involved in the pathogenesis of lupus, via its participation in both the innate and acquired immune response, the exact role of PRL as an immune-stimulatory or immune-inhibitory factor requires careful dissection." (PMID 39000207, 2024). "Similar to that seen in lupus, elevated serum and/or cutaneous PRL levels were reported patients with psoriasis in several small studies, but not universally replicated." (PMID 39000207, 2024). "Because of this, prolactin abnormalities have been described in many autoimmune conditions such as autoimmune uveitis, thyroid disease, and systemic lupus erythematosus." (PMID 39205744, 2024). "The female sex is known to have a greater propensity to develop some autoimmune conditions such as systemic lupus erythematosus and rheumatoid arthritis due to the effect of estrogen and prolactin on the immune system." (PMID 37865776, 2023). "We found that the IL-6 concentration and the percentage of IL-6+ cells increased when the cells were differentiated in the presence of PRL, further supporting that PRL promotes IL-6 secretion in B-GCs in lupus-prone mice." (PMID 36389691, 2022). "• The mean prolactin levels were 6.4, 7.65, and 10.85 in healthy subjects, inactive lupus patients, and active lupus cases, respectively (P=0.01)." (PMID 34447911, 2021). "Comparison of the results of the present research with those of other studies regarding the role of prolactin in systemic lupus erythematosus." (PMID 34447911, 2021). "Prolactin has been reported to exacerbate the clinical manifestations of lupus by increasing autoantibody concentrations." (PMID 33763492, 2021). "Hyperprolactinemia has been reported in 15–33% of patients with lupus, and PRL levels have shown a direct correlation with the clinical and serological disease activity." (PMID 33557010, 2021).
systemic lupus erythematosus (continued). "Prolactin is known to rescue immature B cells from B cell receptor engagement-induced apoptosis in lupus-prone mice." (PMID 33557010, 2021). "In lupus patients, the immunosuppressive effect of T regulator cells over T effector cells is apparently modulated by prolactin secretion." (PMID 32235676, 2020). "In conclusion, the evidence strongly supports the role of PRL in the pathogenesis and activity of systemic lupus erythematosus." (PMID 29483903, 2018). "But for postpartum SLE patients, there were few researches on the relationship between prolactin and lupus activity." (PMID 25973434, 2015). "This preliminary study examined the relevance of a −1149G/T functional single-nucleotide polymorphism (SNP) (rs1341239) in the promoter of the extrapituitary prolactin gene in a cohort of African American and European American women with lupus." (PMID 26583155, 2015). "This investigation has confirmed earlier reports of low levels of DHEA in lupus patients and high levels of prolactin." (PMID 26583155, 2015). "Taken together, these data show that increased PRL concentrations in serum correlates with the early onset of lupus symptoms in lupus-prone mouse strains." (PMID 24454471, 2013). "However, it is worth mentioning that prolactin participates in the pathogenesis and activity of several autoimmune disorders, such as for example systemic lupus erythematosus." (PMID 37122698, 2023). "The linkage between prolactin (PRL) and systemic lupus erythematosus (SLE) is still vague." (PMID 37864188, 2023). "One of the conditions where PRL has such a role is systemic lupus erythematosus (SLE)." (PMID 36389803, 2022). "PRL might be related with “gap junction”, “neuroactive ligand-receptor interaction”, “olfactory transduction”, and “systemic lupus erythematosus”." (PMID 35757392, 2022). "Moreover, multiple reports have shown PRL rs1341239 is related with rheumatoid arthritis (RA) or systemic lupus erythematosus (SLE), in which disturbance of bone metabolism is increased." (PMID 28152004, 2017). "Taking together our observations in the in vitro model of tolerance and in the lupus prone mice, PRL may favor the maturation of self-reactive B-cell clones and contribute to the onset of disease." (PMID 27314053, 2016). "For postpartum lupus patients, our study showed that oral bromocriptine therapy after delivery could not only reduce serum prolactin level quickly but also be helpful to decrease serum estradiol concentration to pregestation level rapidly." (PMID 25973434, 2015). "In addition to high levels of prolactin, lupus patients have low serum levels of dehydroepiandrosterone (DHEA)." (PMID 26583155, 2015). "Higher levels of prolactin were noted in the serum of lupus patients (p = 0.0026)." (PMID 26583155, 2015). "However, several recent publications have reawakened interest in the “PRL-skin” connection, particularly in the context of a possible role for PRL in psoriasis and systemic lupus erythematosus." (PMID 23626671, 2013). "This might be an important mechanism for breakdown of tolerance, since PRL-enhanced BIRC5 expression correlated with an early onset of lupus symptoms." (PMID 24454471, 2013). "The objective of this study was to determine whether different splenic B cell subsets express the PRL receptor and if the presence of PRL influences these B cells subsets and correlates with the development of lupus." (PMID 22404893, 2012). "The prolactin gene −1149 G/T polymorphism has also been associated with lupus and rheumatoid arthritis, although this finding could not be replicated for the former in a meta-analysis." (PMID 39000207, 2024). "However, we caution that prolactin mimicking effects may worsen auto-immune disease symptoms in patients suffering from systemic lupus erythematosus (SLE), multiple sclerosis, rheumatoid arthritis, psoriatic arthritis, and AIDS." (PMID 37658087, 2023).